TREM2 (triggering receptor expressed on myeloid cells 2)
Diseases named in the same sentence as TREM2 in open-access papers (continued):
Sharing a sentence is not in itself a finding about the gene and the disease.
cancer (continued). "Previous research has proved that high TREM2 level predicts poor prognosis in various cancers." (PMID 41253786, 2025). "TREM2, as an immune signaling hub mediating multiple pathological pathways, is widely expressed on immune cells with important pro-immunosuppressive effects, and plays a great role in cancer immunotherapy." (PMID 38725629, 2024). "Additionally, TREM2 expression in cancer cells directly facilitates their survival, as observed in esophageal adenocarcinoma." (PMID 39135069, 2024). "TREM2 in TAMs fosters an immunosuppressive TME in different cancers." (PMID 39135069, 2024). "TREM2 have different roles in various pathologies, cancer and cell types." (PMID 37335084, 2023). "We started more broadly, merging scRNA-Seq datasets of BCC myeloid cells with myeloid cells (dendritic and macrophages) with other datasets that have examined the role of Trem2+ cells from different tissue contexts including normal skin, wounded skin, various cancers, and microglia 22,23,30,32,33." (PMID 37164949, 2023). "Finally, an integrated transcriptomic analysis from multiple datasets of human cancers identified TREM2-expressing TAMs in lung, colon, liver, breast, stomach, pancreas, ovaries, skin, kidney, as well as head and neck cancers." (PMID 35746551, 2022). "Here, we review the current knowledge about the impact of TREM2 in cancer, with an emphasis on the TREM2+ macrophage signature across different cancer types, the contribution of TREM2 to TAM phenotype and function, and the promising effects of TREM2 modulation." (PMID 35746551, 2022). "Overall, the literature reveals TREM2 could be considered a novel therapeutic target for certain types of cancer." (PMID 36119485, 2022). "Indeed, some fundamental research has identified TREM-2 as a valuable therapeutic target for cancer immunotherapy." (PMID 35875168, 2022). "However, the literature consistently reports that TREM2 expression by immune cells creates an immunosuppressive environment that allows the cancer cells to thrive." (PMID 36119485, 2022). "Recently, TREM2 was identified as a potential therapeutic target in cancer therapy." (PMID 36230558, 2022). "However, expansion of TREM2 research into the field of cancer has revealed that epithelial tumor cells as well as intratumoral macrophages and myeloid regulatory cells also express TREM2." (PMID 36119485, 2022). "Moreover, the potential impact of soluble TREM2 in the context of cancer needs to be further elucidated." (PMID 35746551, 2022). "A further mechanistic understanding of TREM2 expression regulators and their downstream signaling pathways is expected to enable the development of effective immunotherapies targeting these myeloid mediators in cancers, including HCC." (PMID 35359989, 2022). "Mounting evidence has revealed an immunosuppressive role of TREM2 in cancer." (PMID 35967424, 2022). "These deviations in expression of TREM2 indicate that TREM2 may serve distinct roles and may exhibit differing levels of influence in distinct types of cancer." (PMID 36119485, 2022). "Additionally, TREM2 is regarded as a prognostic marker in several cancers, and the expression of TREM2 in these tumors is positively related to the infiltration level of most immune cells." (PMID 36360294, 2022). "Multiple pan-cancer studies also identified the TREM2 signature." (PMID 35746551, 2022). "As we learn more about the roles of TREM2 expressed by differing cell types, the utilization of scRNAseq may be critical to advancing our knowledge and understanding of TREM2 in cancer." (PMID 36119485, 2022). "The seeming discrepancy between TREM2 benefitting or worsening patient prognosis in different types of cancer may at first seem puzzling; however, the investigators dove deeper to better understand TREM2 in each cancer type." (PMID 36119485, 2022). "However, more recently, TREM2 has been identified on certain epithelial-derived cancer cells and its expression influences their behavior." (PMID 36119485, 2022).
cancer (continued). "Current knowledge suggests that TREM2 expression on cells of the monocyte-macrophage lineage may also serve an immunoregulatory role in cancer, creating an immunosuppressive environment." (PMID 36119485, 2022). "Recent studies have identified TREM2 as an emerging therapeutic target for cancer immunotherapy." (PMID 36438899, 2022). "Thus, we aimed to explore the prognostic value, and investigate the potential immunological functions, of TREM2 across 33 cancer types." (PMID 33679809, 2021). "Based on existing research and our findings, we infer that tumors with high TREM2 expression, and high TMB and MSI may have a better prognosis after ICI treatment in cancers where TREM2 expression is positively correlated with TMB." (PMID 33679809, 2021). "Our results show that TREM2 plays an essential role in cancer immunity." (PMID 33679809, 2021). "Furthermore, our enrichment analyses indicated that TREM2 can potentially impact cancer etiology or pathogenesis by functioning in cell adhesion; B/T cell activation, immune response, immune regulating, and signaling; RNA metabolism; and metabolic pathways." (PMID 33679809, 2021). "Relationship between TREM2 expression and immune cell infiltration in different cancers." (PMID 33679809, 2021). "We found that TREM2 expression was correlated with DNA methylation, and that TREM2 methylation level could serve as a biomarker of prognosis in patients with cancer." (PMID 33679809, 2021). "Next, we analyzed TREM2 expression levels in various cancers and ranked them from low to high." (PMID 33679809, 2021). "Additionally, TREM2 expression was associated with TMB and MSI in 12 cancer types, while in 20 types of cancer, there was a correlation between TREM2 expression and DNA methylation." (PMID 33679809, 2021). "We have recently reported that TREM2 is selectively expressed on TAMs in various human cancer." (PMID 34220848, 2021). "In cancer, Trem2 was suggested to be a key regulator of myeloid suppressive cells." (PMID 33557250, 2021). "Moreover, TREM2 expression was associated with TMB, MSI, and immune cell infiltration across various cancer types." (PMID 33679809, 2021). "Second, given that TREM2 can be released as a soluble form, the biological and clinical significance of soluble TREM2 in the context of cancer might also reveal additional roles of TREM2." (PMID 33037186, 2020). "We found that 30 of these genes which included Nckap1l, Ncf1, Pla2g15, Unc93b1, Lrrc33, Rgs10, Gmfg, Rbm25, C3ar1, Ccdc88b, Fam105a, Gng11, Phc1, Rasa4, Dag1, Tyrobp, Tmsb4x, Cfp, Prkd1, Gp49a, Trem2, C1qc, Lyz2, Igfbp7, Rab30, Cxcl16, Egfl7, Ube2r2, Pltp, and Cfb, showed a relation with cancer." (PMID 32812032, 2020). "TREM2 and CD180 are negative regulators of the Toll-like receptor pathway, a family of receptors that recognize damage-associated molecule patterns, whose increased serum levels have been associated with cancer." (PMID 28927421, 2017). "Therefore, inhibiting TREM2 holds promise as an effective approach of eliminating cancer cells." (PMID 40242752, 2025). "Notably, TREM2 is implicated in the development and progression of multiple diseases, playing dual and often opposing roles in noncancerous diseases and cancers." (PMID 40242752, 2025). "Furthermore, our analysis of the association between GZMK, TREM2, and OR4D10 expression and cancer patient prognosis in the TCGA cohort demonstrated that reduced expression of GZMK and increased expression of TREM2 and OR4D10 were significantly correlated with poor prognosis in THCA." (PMID 40332815, 2025). "Additionally, TREM2 alone does not reliably predict cancer prognosis, as other TREM2+ macrophages show varied associations with prognosis depending on local cues." (PMID 38972873, 2024). "However, the role of TREM2 in human cancer is poorly understood." (PMID 35359989, 2022). "In addition, we discovered that TREM2 expression is related to age in some types of cancer." (PMID 33679809, 2021).
cancer (continued). "Even though few clinical studies about targeting TREM2 in cancer treatment are conducting now, the potential for clinical translation of TREM2-targeted therapies remains high in the future, and numerous possible interventions are existed to tackle the TREM2 and its signaling pathway." (PMID 34539652, 2021). "Our findings suggest that TREM2 can be served as an independent prognostic factor of many tumors and for different tumors, the level of its expression level will bring different prognostic outcomes, which needs to be further studied for the specific role of TREM2 in each cancer." (PMID 33679809, 2021). "Here, we found that TREM2+ TAMs were accumulated in GC, promoting PD-L1 expression and CCL8 secretion through STAT1-enhanced transcription, leading to cancer progression and CD8+ T cell exhaustion." (PMID 41253786, 2025). "Among cancer cell receptors, SPP1, MK, and TWEAK were identified as potential recipients, with the SPP1–CD44 axis mediating interactions with TREM2 TAMs, consistent with recent studies." (PMID 41228323, 2025). "Genotype–tissue expression pan-cancer data and The Cancer Genome Atlas (TCGA) were used to investigate the expression of GZMK, TREM2, and OR4D10." (PMID 40332815, 2025). "There were also significant interactions between insulin-expressing cancer cells and immune cells, namely CD40LG (INS+FOSlow, INS+) − CD40 (B cell) and APP (INS+) − TREM2 + TYROBP (macrophage)." (PMID 40438247, 2025). "The results demonstrated that a poor prognosis in THCA was substantially correlated with reduced expression of GZMK, TREM2, and OR4D10 (p = 0.041, 0.024, and 0.017), suggesting that GZMK, TREM2, and OR4D10 are the potential oncogenes in this cancer." (PMID 40332815, 2025). "First, we looked at the expression of GZMK, TREM2, and OR4D10 in the pan-cancer datasets GTEx and TCGA." (PMID 40332815, 2025). "Oxidized LDL polarizes TREM2+ TAMs via the TREM2-SYK-CEBPα axis, enabling the TAMs to enhance cancer cell invasion, cytokine resistance, and CD8+ T cell dysfunction." (PMID 41417432, 2025). "Among these, GZMK, TREM2, and OR4D10 have emerged as promising candidates due to their involvement in immune regulation and cellular processes that are often dysregulated in cancer." (PMID 40332815, 2025). "To assess the usefulness of GZMK, TREM2, and OR4D10 expression in predicting the prognosis of cancer patients, we examined the relationship between GZMK, TREM2, and OR4D10 expression and overall survival in the TCGA cohort." (PMID 40332815, 2025). "For example, C1q, TREM2, and FOLR2 are all key biomarkers for identifying TAM subsets in various cancers." (PMID 38303024, 2024). "While the role of TREM2 in GBM has only just begun to be investigated since the TME and TAMs came to the attention of researchers, its roles in other cancer treatments began much earlier." (PMID 38203185, 2023). "In myeloid cells, the top 50 pan-cancer central genes included seven genes involved in myeloid cell differentiation (CD4, FCER1G, IRF8, TYROBP, TLR2, TREM2 and ITGAM), but only two of them (FCER1G and TYROBP) were found among the top 50 DEGs." (PMID 36350625, 2023). "According to ESTIMATE scores, there were positive correlations between TREM2 expression and both stromal and immune cell content in the TME of 30 cancers." (PMID 33679809, 2021). "Indeed, we identify several populations of macrophages in CKD, including FOLR2+ and TREM2+ macrophages, two TAM subsets recently discovered in cancer and still poorly described in kidney." (PMID 38272907, 2024). "Our study built upon these findings and proposed that the TREM2+ TAM subpopulation could serve as an alternative origin or result of complement activation, resulting in the blockade of the cancer immunity cycle." (PMID 37187751, 2023).
cancer (continued). "Collectively, this suggests that a rationally designed ligand-independent TREM-2 inhibitory peptide sequence IA9 can be a promising alternative to ligand-dependent anti-TREM-2 mAbs to modulate local inflammation in the management of RA, IBD, cancer and, probably, other inflammatory diseases." (PMID 36012120, 2022). "Among CD68+CD163+ TAMs also expressing the recently identified TREM2 marker, we could identify a CXCL10+IRF1+STAT1+ M1-type Mφ population (Cluster 9) shared between all cancer types." (PMID 34220848, 2021). "Hence, it is important to further explore the pan-cancer relationship between TME and TREM2 expression." (PMID 33679809, 2021). "Although increasing evidence supports a vital role for TREM2 in tumorigenesis of some cancers, no systematic pan-cancer analysis of TREM2 is available." (PMID 33679809, 2021). "Even if not directly to AD, the pathways involved in TREM2 protective role have been better dissected in cancer models." (PMID 33768114, 2020). "While there is much to learn about the role of TREM2 in cancer, some key studies indicate that TREM2 is involved in suppressing the function of CD8+ T cells as well as inhibiting their proliferation, which would argue for myeloid-targeted inhibition of TREM2 at least in some cancers." (PMID 36119485, 2022). "However, the importance of TREM2 in cancer has recently come to light, although it is not yet widely studied or understood, hence the focus on cancer for this review." (PMID 36119485, 2022). "The TREM2 expression profile on the cancer cells injected in these studies was not reported." (PMID 36119485, 2022). "Therefore, we used multiple databases, including TCGA, Cancer Cell Line Encyclopedia (CCLE), Genotype Tissue-Expression (GTEx), cBioPortal, and Human Protein Atlas (HPA), to analyze TREM2 expression levels and their relationship with prognosis in different types of malignancy." (PMID 33679809, 2021). "Therefore, we next investigated the role of TREM2+ macrophages in the development of non-cancerous and cancerous diseases, including metabolic, neurological, pulmonary, and cardiovascular diseases and cancers." (PMID 40242752, 2025). "However, for silvestrol we could show that it potentially strengthens the M2 phenotype by reducing expression of CD206, TREM2 and decreasing the release of pro-inflammatory IL-8 and CCL2, thereby possibly weakening the host’s immune defense against cancer by exhausting CD8+ T cells." (PMID 39518983, 2024). "The effectiveness of TREM2 blockade in these models suggests that TREM2+ TAM plays a widespread functional role during tumorigenesis, and indeed TREM2+ TAM could be detected in a large number of different human carcinoma types, including lung, colon, liver, breast, stomach, and pancreas datasets." (PMID 39430099, 2024). "We also determined that TREM2+ TAMs highly expressed soluble factors such as SPP1, APOE, C1QA, C1QB, and C1QC, which suggested that this TREM2+ TAMs subset may be exocrine or paracrine for establishing the microflora critical for cancer cell invasion and the metastasis environment." (PMID 37187751, 2023). "However, the role of TREM-2 signaling in cancer has never been elucidated." (PMID 27102437, 2016).
infection (54 papers, 2013 to 2026). The state of being infected such as from the introduction of a foreign agent such as serum, vaccine, antigenic substance or organism. "Trem2 is also implicated in various pathogenic infections due to its ability to recognize and bind pathogens, subsequently, facilitating innate immune responses against pathogens (e.g., Syk-dependent phagocytosis)." (PMID 39250507, 2024). "Cytotoxicity assay confirmed that TREM2 deficiency enhances infection-leaded cell death as the release of LDH in KO cells was significantly higher that WT cells." (PMID 36068223, 2022). "One study reported that Kupffer cells that express CD68 support the entry of sporozoites to cause infection, while another showed that Kupffer cells that express triggering receptor expressed on myeloid cells 2 (TREM2) are able to reduce hepatocyte infection." (PMID 34271941, 2021). "Tyrobp (DAP-12 adapter) and its related receptors Trem2 and Clec5a are consistently up-regulated, while signaling genes have a mixed response in terms of association with infection, with about half of these genes being up-regulated." (PMID 27058578, 2016). "TREM-2 deficient mice exhibited a thousand fold decrease in S. pneumoniae burden in lungs 48 h post infection." (PMID 24945405, 2014). "Whether the loss of TREM2 affects the function of recruited neutrophils and whether the neutrophils recruited to the site of infection have effect on the prognosis remains to be further studied." (PMID 38236825, 2024). "It has been reported that Trem2-/- mice are more susceptible to pathogen infection." (PMID 39250507, 2024). "We could therefore hypothesize that the anti-inflammatory phenotype and the reduced bacterial loads seen in TREM-2 deficient mice are a result of decreased intracellular bacterial replication at the infection site, due to reduced neutrophilic influx." (PMID 27253382, 2016). "Once infection is resolved, their population contracts to baseline levels, but by day 14 post‐infection, they undergo functional diversification, giving rise to Trem2+ Reg‐Ms and Fbp1+ Prolif‐Ms that promote inflammation resolution and tissue repair." (PMID 41271590, 2026). "Meanwhile, the expressions of Slc11a1, Havcr2, Ccl12, Sirt1, Ifng, Ccl3, and Trem2 were higher during the whole infection process." (PMID 40170749, 2025). "Nevertheless, the enhanced suppression of MICAL1 and P-ERK upon the infection in Trem2−/− mice indicates that Trem2 likely plays a critical protective role during the infection, alleviating the parasite’s ability to over-suppress MICAL1/P-ERK signaling." (PMID 41305343, 2025). "In experiments using mouse models of simulated infection, researchers have found that TREM2 can negatively regulate the TLR4 signaling pathway to inhibit the inflammatory response in early stage gram-negative bacteremia." (PMID 40242752, 2025). "Consistent with this, a large number of neutrophils were present at the site of infection in Trem2-/- mice stimulated by P. aeruginosa and components of M. tuberculosis." (PMID 38236825, 2024). "Intracellular ROS production is dependent on TREM2 and is responsible for the removal of S. typhimurium or P. aeruginosa, while in infection with M. tuberculosis and E. coli, overexpression of TREM2 leads to a decrease in ROS." (PMID 38236825, 2024). "Of note, the current studies on regulation of parenchymal cell metabolism by TREM2 during infection mostly focused on TREM2-mediated phagocytosis to reduce cell production of harmful substances." (PMID 38236825, 2024). "First, most of the infection-related findings have been performed in Trem2 knockout mice, but TREM molecules are different between mice and humans." (PMID 38236825, 2024). "Consistently, our study showed the elevated IL-1β in the placentas of Trem2-/- mice compared to wildtype mice following infection." (PMID 39250507, 2024).